ITGB8 (integrin subunit beta 8)
Diseases named in the same sentence as ITGB8 in open-access papers (continued):
Sharing a sentence is not in itself a finding about the gene and the disease.
colitis (7 papers, 2011 to 2022). Inflammation of the colon. "Loss of either major histocompatibility complex class II (MHCII) or ITGB8 by Thetis cells led to a profound impairment in intestinal pTreg differentiation, with ensuing colitis." (PMID 36070798, 2022). "Itgb8-/- Tregs were capable of preventing colitis when they were co-transferred with naïve T cells to Rag1-/- mice." (PMID 34302795, 2021). "Functionally, Tregs from ITGB8 knockouts (KO) exhibit normal suppressor function in in vitro and in vivo models of colitis, but fail to provide TGF-β1." (PMID 29176973, 2017). "For example, conditional deletion of Itgb8 in hematopoietic cells and and dendritic cells of mice induced late-onset autoimmune syndrome characterized by splenomegaly, hepatitis, and colitis with death between 4 and 10 months of age33." (PMID 28874788, 2017). "Next, to test whether there was any defect when transferred to an inflammatory environment, we performed transfer colitis experiments, analyzing control or Itgb8 KO Treg cells transferred to colitic Rag2−/− mice that had received naive CD4+ T cells 2 weeks earlier." (PMID 25979421, 2015). "In dextran sulphate sodium‐mediated colitis, the lack of Itgb8+ Tregs also exacerbates pathology, including the elevation of CD4+ T cells without altering Treg migration, activation or stability." (PMID 32463116, 2020). "However, Itgb8-/- Tregs failed to control ongoing colitis when they were injected two weeks after the transfer of naïve T cells in Rag1-/- mice." (PMID 34302795, 2021). "Likewise, a more severe colitis is observed when transferring Itgb8‐negative Tregs into inflamed Rag2−/− recipients." (PMID 32463116, 2020). "One potential caveat to this observation is that inflammation present when Itgb8 KO Treg cells do not rescue colitis might affect pSmad2/3 signaling." (PMID 25979421, 2015). "Treg cells lacking expression of integrin β8 could not rescue colitis, which meant that control and Itgb8 KO Treg cells were subjected to different intestinal environments." (PMID 25979421, 2015).
prostate carcinoma (7 papers, 2015 to 2025). A carcinoma that arises from epithelial cells of the prostate gland. "A nomogram was constructed that contained four variables (ITGB8, hsa-miR-21, hsa-miR-30b and prostate-specific antigen (PSA) value) for predicting the risk of prostate cancer." (PMID 35957689, 2022). "The high level of expression of both EPHB4 and ITGB8 in clinical PIN samples suggests that their increased expression is an early event in the development of prostate cancer." (PMID 25886373, 2015). "Knockdown of ITGB8 in PC-3 and 22Rv1 prostate cancer cells in vitro resulted in significant reduction of cell migration and invasion." (PMID 25886373, 2015). "This also identifies a new mechanism for EphB4 function in prostate cancer through the regulation of ITGB8, which our results show can contribute to prostate cancer cell motility." (PMID 25886373, 2015). "The interaction network showed that hsa-miR-21, hsa-miR-30b, and ITGB8 may be utilized as new biomarkers for prostate cancer." (PMID 35957689, 2022). "It would be interesting to investigate whether the transcription factors of the SP family can also influence EPHB4 expression in prostate cancer and thus be responsible for co-regulating ITGB8 and EPHB4." (PMID 25886373, 2015). "Together, these data suggest that EPHB4 and ITGB8 are co-regulated in prostate cancer cells." (PMID 25886373, 2015). "Additionally, the expression level of ITGB8 can be regulated by the tumor-promoting receptor tyrosine kinase-EphB4, while knockdown of ITGB8 may suppress migration and invasion in prostate cancer cell lines." (PMID 31875161, 2019). "As the expression of integrin β8 has been found to be increased in metastases from various tumors, including breast and lung, we speculated that integrin β8 could also play a role in prostate cancer cell migration and invasion and we show that silencing of ITGB8 reduces cell motility." (PMID 25886373, 2015). "In prostate cancer cell lines, CAV1, PALLD, and ITGB8 are upregulated, while CLDN7 is downregulated." (PMID 40002724, 2025). "The expression levels of CAV1, PALLD, ITGB8, and CLDN7 were analyzed using RT-qPCR in the normal prostate epithelial cell line RWPE1 and four prostate cancer cell lines: LNCaP, 22RV1, DU145, and PC3." (PMID 40002724, 2025). "By interrogating the Oncomine database we have identified ITGB8 as being up-regulated in PIN, the precursor to prostate cancer which is puzzling considering its role in metastases." (PMID 25886373, 2015). "In the current study, validation experiments confirmed that ITGB8 was significantly down-regulated when EPHB4 was knocked down and moreover, was also up-regulated when EPHB4 was over-expressed in prostate cancer cells." (PMID 25886373, 2015). "In silico analysis of a prostate cancer progression microarray publically available in the Oncomine database showed that both EPHB4 and ITGB8 are highly expressed in prostatic intraepithelial neoplasia, the precursor to prostate cancer." (PMID 25886373, 2015). "This could indicate that EPHB4, ITGB8 and TGFB1 are intrinsically regulated in prostate cancer cells, therefore contributing to cancer progression and metastasis through the process of EMT." (PMID 25886373, 2015). "However, by using logistic regression strategy, we found and validated that several VUS-containing genes (COL1A1, CSF3R, ERBB2, ITGB8, TSC1 and TSC2) in the PI3K-Akt signaling pathway can improve the predicting of metastasis in prostate cancer patients in Hong Kong and Shanghai cohorts." (PMID 36095024, 2022).
breast carcinoma (6 papers, 2015 to 2023). "Furthermore, ITGB8 has been identified as a member of a six-gene expression signature biomarker predicting lung metastasis from breast cancer." (PMID 25886373, 2015). "ANP32E along with desmocollin 2 (DSC2), UDP glycosyltransferase 8 (UGT8), Integrin subunit beta 8 (ITGB8) and Fermitin family member 1 (FERMT1) is found to predict lung metastasis of breast cancer patients and has been used as prognostic marker." (PMID 32257110, 2020). "The miRNA let-7b-5p was also shown to have a tumor suppressor role in breast cancer patients with lymph node metastasis, by repressing the expressions of the genes PAK1, DIAPH2, RDX and ITGB8." (PMID 26763900, 2015). "These genes (COL9A1, ITGB8, ITGB6, TTYH1, RET, etc.)enriched in the cell adhesion may serve as important indicators of different types of breast cancer." (PMID 26273658, 2015).
melanoma (5 papers, 2007 to 2025). A malignant, usually aggressive tumor composed of atypical, neoplastic melanocytes. "We analyzed 358 patients bearing melanoma and revealed that high ITGB8 score in tumor-infiltrating T cells was associated with poor survival." (PMID 34711823, 2021). "The differential effect of miR-17-5p and miR-20a on gene expression in melanoma cells was further studied by focusing on four TargetScan-predicted target genes: ITGB8, TGFR2, MMP2 and VEGF-A." (PMID 24920276, 2014). "Ectopic expression of these miRNAs in melanoma cells differentially alters the expression of five exemplar TargetScan-predicted target genes: ADAR1, ITGB8, TGFBR2, MMP2 and VEGF-A." (PMID 24920276, 2014). "Both melanoma cell lines showed a comparable viral entry receptor expression profile, with high expression of TNFRSF14 and ITGB8 and low expression of all other genes, which might explain their similar sensitivity to infection with oHSV1-FLT3L." (PMID 40955425, 2025).
colorectal cancer (4 papers, 2020 to 2023). A primary or metastatic malignant neoplasm that affects the colon or rectum. "For example, ectopic expression of ITGB8 enhanced proliferation and invasion of colorectal cancer cells." (PMID 32565741, 2020). "Additionally, overexpression of ITGB8 led to the growth and metastasis of colorectal cancer." (PMID 35676251, 2022).
dilated cardiomyopathy (3 papers, 2017 to 2025). Cardiomyopathy which is characterized by dilation and contractile dysfunction of the left and right ventricles. "The two differentially expressed genes ITGA4 and ITGB8 are present in heart disease-related pathways, including Dilated Cardiomyopathy (DCM), Arrhythmogenic Right Ventricular Cardiomyopathy (ARVC), and hypertrophic cardiomyopathy (HCM)." (PMID 28692647, 2017).
inflammatory bowel disease (3 papers, 2017 to 2025). A spectrum of small and large bowel inflammatory diseases of unknown etiology. "Mice with silenced β8 encoding gene ITGB8 die either at midgestation or shortly after birth, and conditional knockout of ITGB8 results in severe inflammatory bowel disease." (PMID 39743547, 2025). "In murine models, the conditional knockout of ITGB8 on leukocytes leads to the development of severe inflammatory bowel disease and age-associated autoimmune disorders." (PMID 39743547, 2025). "Supporting this hypothesis, a prior genome-wide association study identified associations between inflammatory bowel disease susceptibility and increased immune activation of specific integrin genes (ITGA4, ITGB8, ITGAL, and ICAM1)." (PMID 39982236, 2025).
lung adenocarcinoma (3 papers, 2020 to 2021). A carcinoma that arises from the lung and is characterized by the presence of malignant glandular epithelial cells. "The bioinformatics analysis revealed that ITGB8 is significantly upregulated in patients with lung adenocarcinoma, which may become a diagnostic biomarker." (PMID 33335550, 2020).
non-small cell lung carcinoma (3 papers, 2019 to 2024). A group of at least three distinct histological types of lung cancer, including non-small cell squamous cell carcinoma, adenocarcinoma, and large cell carcinoma. "Similarly, ITGB8 has been reported to promote metastasis in colorectal and non-small cell lung cancers." (PMID 38814534, 2024).
pulmonary fibrosis (3 papers, 2021 to 2024). Chronic progressive interstitial lung disorder characterized by the replacement of the lung tissue by connective tissue, leading to progressive dyspnea, respiratory failure, or right heart failure. "Interleukin-1β (IL-1β), a crucial pro-inflammatory cytokine implicated in lung fibrosis, increases ITGB8 expression in the lung fibroblasts, which increases αvβ8-mediated TGFβ activation in fibrosis and pathologic inflammation." (PMID 39684311, 2024). "SPP1, THBS2, ITGB8, and some other genes screened out in this study have rarely been studied in the pathogenesis of pulmonary fibrosis, which also suggests possible approaches for subsequent pathogenesis studies." (PMID 33672678, 2021). "The mRNA expression of Itga11, Itgb8, Thbs1, and Thbs2 was significantly upregulated in the o-PF group, indicating the stronger activity of TGF-β in old rats when pulmonary fibrosis occurs." (PMID 36556326, 2022).
Bladder Cancer (2 papers, 2025). "A recent study highlighted the considerable upregulation of TRIM59 in recurrent bladder cancer, involving the F-actin/ITGB8/TRIM59/AKT/mTOR/glycolysis pathways." (PMID 40796729, 2025).
brain tumor (2 papers, 2023). "Moreover, in brain tumors, ITGB8 and ITGAV integrins show the highest expression in primary proneural and mesenchymal gliomasphere cultures, while their interaction with the integrin-binding syalo-protein IBSP promote tumor cell migration." (PMID 37835469, 2023). "Next, we evaluate whether the high expressions of collagen type I receptors (ITGAV, ITGB8, SDC1, SDC4, and CD44) in tumor tissues, i.e., tumor receptors, are related with the prognosis of patients with brain tumor." (PMID 37479733, 2023).
COVID-19 (2 papers, 2022 to 2024). A disease caused by infection with severe acute respiratory syndrome coronavirus 2. "Integrin-related genes, including ITGA1, ITGB3, ITGB5, and ITGB8, have been less investigated in patients with COVID-19 myocarditis and may be potential prognostic biomarkers." (PMID 39026189, 2024). "Seven common DEGs (PPARGC1A, FUBP1, ITGB8, SYCP2, RSAD2, FGF1, and FERMT1) were identified from the GSE164805 dataset of patients with mild COVID-19, and the GSE50395 dataset from APS patients." (PMID 36241659, 2022).
diabetes (2 papers, 2021 to 2023). "Moreover, COL4A1 in mesangial cells, the expression of which was increased in diabetes, acted on ITGB8 in glomerular endothelial cells." (PMID 34222276, 2021).
lung squamous cell carcinoma (2 papers, 2022 to 2024). "In lung squamous cell carcinoma, it promotes proliferation, migration, and tumor progression by modulating the expression of Bcl-2 and Bax, enhancing ITGB8 expression, and binding to miR-299-3p, resulting in elevated MAP3K2 expression." (PMID 38612418, 2024).
atherosclerosis (1 paper, 2025). A disease characterized by the build-up of fatty material and calcium deposition in the arterial wall resulting in partial or complete occlusion of the arterial lumen. "The aberrant expression of Itga1 and Itgb8 could impair vascular remodeling and endothelial integrity, thereby promoting the progression of atherosclerosis." (PMID 40941321, 2025).
Autoimmunity (1 paper, 2024). The occurrence of an immune reaction against the organism's own cells or tissues. "The ITGB8-mediated immune pathway is essential for preventing immune dysfunction, autoimmunity, and IBD." (PMID 39275347, 2024).
dry eye (1 paper, 2023). "ITGB1 and especially ITGB8 are down-regulated in patients with dry eye." (PMID 38254630, 2023).
hemorrhage (1 paper, 2022). Loss of blood from the vascular compartment to the exterior or into nonvascular body space as a result of rupture or severance of the blood vessels. "In Itgb8 KO and Nestin-Cre;Itgb8-flox mice, cerebral hemorrhage and abnormal brain capillaries, including bulbous endothelial cell clusters, were observed." (PMID 36362915, 2022).
human papillomavirus infection (1 paper, 2021). "It is worth noting that one of the plasma membrane expressed proteins, ITGB8, is associated with 4 of the 9 enriched KEGG pathways, including ‘ECM-receptor interaction,’ ‘focal adhesion,’ ‘PI3K-Akt signaling pathway,’ and ‘human papillomavirus infection’." (PMID 33430025, 2021).
ovarian tumor (1 paper, 2024). "GSE133859 provided paired OC samples, which demonstrated that ITGB3, ITGB4, ITGB7, and ITGB8 increased in ovarian tumor tissue compared with normal tissue." (PMID 38814534, 2024).
renal fibrosis (1 paper, 2019). A final common manifestation of a wide variety of chronic kidney diseases characterized by glomerulosclerosis and tubulointerstitial fibrosis. "Therefore, up-regulation of ITGB8 would be expected in renal fibrosis, which might lead to sustained activation of TGF-β signaling, thus forming a positive feedback activation loop." (PMID 31455266, 2019).
Renal insufficiency (1 paper, 2024). A reduction in the level of performance of the kidneys in areas of function comprising the concentration of urine, removal of wastes, the maintenance of electrolyte balance, homeostasis of blood pressure, and calcium metabolism. "In clinical validation, compared with healthy controls or with increasing age, transcriptomic data from the renal tissues of DN patients showed a significant downregulation of ITGB8 expression, suggesting that ITGB8 could serve as a valuable indicator of renal insufficiency." (PMID 39725889, 2024).
serous ovarian cancers (1 paper, 2022). "Moreover, expression of ITGB8 contributed to unfavorable prognosis of high grade serous ovarian cancers." (PMID 35676251, 2022).
squamous cell carcinoma (1 paper, 2022). A carcinoma arising from squamous epithelial cells. "The PFS of the patients with low ITGB8 expression was longer than that of the patients with high ITGB8 expression; which showed with non-responders in squamous cell carcinoma." (PMID 35135489, 2022). "In non-responders with squamous cell carcinoma, LAMB3, ITGB8, and WNT5A genes were highly expressed." (PMID 35135489, 2022).
Stroke (1 paper, 2021). Sudden impairment of blood flow to a part of the brain due to occlusion or rupture of an artery to the brain. "Specifically, when comparing MCAO vs. sham, proteins FBXO7, WIPI2, NTRK2, A0A0G2JY03, and ITGB8 appeared clearly underexpressed, whereas MAP1a and CPQ were overexpressed, indicating a clear effect of the stroke (MCAO injury) on the individuals." (PMID 35008673, 2021).